WNT10A (Wnt family member 10A)
Description:
Ligand for members of the frizzled family of seven transmembrane receptors (Probable). Functions in the canonical Wnt/beta-catenin signaling pathway (By similarity). Plays a role in normal ectoderm development. Required for normal tooth development. Required for normal postnatal development and maintenance of tongue papillae and sweat ducts. Required for normal proliferation of basal cells in tongue filiform papillae, plantar epithelium and sweat ducts. Required for normal expression of keratins in tongue papillae (By similarity). Required for normal expression of KRT9 in foot plant epithelium. Required for normal hair follicle function.
Synonyms: ECTD16; OODD; SSPS; STHAG4
Tractability: Antibody: UniProt places it where antibodies can reach, with high confidence; its Gene Ontology location is reachable by antibodies, with high confidence; UniProt predicts a signal peptide or a membrane-spanning region.
Gene: Protein-coding gene on chromosome 2 (218,880,852 to 218,899,581, forward strand). Ensembl gene ENSG00000135925.
Subcellular location: Secreted, extracellular space, extracellular matrix; Secreted
Pathways (Reactome):
Signal Transduction: Class B/2 (Secretin family receptors); WNT ligand biogenesis and trafficking
Gene Ontology:
Molecular function: receptor ligand activity; cytokine activity; frizzled binding; signaling receptor binding
Biological process: canonical Wnt signaling pathway; cellular response to transforming growth factor beta stimulus; epidermis morphogenesis; hair follicle development; hair follicle morphogenesis; odontogenesis; sebaceous gland development; skin development; tongue development; cell fate commitment; neuron differentiation; animal organ development; Wnt signaling pathway
Cellular component: extracellular region
Genetic constraint (gnomAD): Loss-of-function variants: 37 observed, 32.78 expected, observed/expected ratio (o/e) 1.13, 90% interval 0.87 to 1.48. The upper end of that interval is the gene's LOEUF score, 1.48, which puts it in group 6 of 6, group 1 being the genes least tolerant of losing a copy. Missense variants: 613 observed, 560.89 expected, observed/expected ratio (o/e) 1.09, 90% interval 1.02 to 1.17. Synonymous variants: 255 observed, 231.33 expected, observed/expected ratio (o/e) 1.1, 90% interval 0.99 to 1.22.
Gene-disease validity (ClinGen):
ClinGen rates the evidence that WNT10A causes each of these diseases.
ectodermal dysplasia WNT10A related (semidominant): Definitive.
Homologues: Orthologues: chimpanzee WNT10A (100% identical), macaque WNT10A (100% identical), dog WNT10A (97% identical), rabbit WNT10A (97% identical), guinea pig WNT10A (96% identical), rat Wnt10a (95% identical), mouse Wnt10a (95% identical), pig WNT10A (95% identical), tropical clawed frog wnt10a (72% identical), zebrafish wnt10a (69% identical), Drosophila melanogaster Wnt10 (43% identical), Drosophila melanogaster Wnt5 (31% identical), and 4 more. Paralogues in human: WNT10B (58% identical), WNT2B (36% identical), WNT5B (35% identical), WNT4 (35% identical), WNT6 (35% identical), WNT7B (35% identical), WNT1 (35% identical), WNT5A (35% identical), WNT7A (35% identical), WNT3A (34% identical), WNT3 (34% identical), WNT2 (32% identical), and 6 more.
Diseases named in the same sentence as WNT10A in open-access papers:
WNT10A is named in the same sentence as 111 diseases in open-access papers, as found by Europe PMC text mining. Sharing a sentence is not in itself a finding about the gene and the disease. The quoted sentences say what the papers report.
tooth agenesis (48 papers, 2012 to 2025). A tooth disease characterized by failure to develop one or more missing teeth. "This study aimed to perform the mutational profiling of WNT10A in saliva samples from Korean children and adolescents with non-syndromic tooth agenesis." (PMID 39941240, 2025). "In this study, we conducted a comprehensive profiling of mutations within the exons and introns of WNT10A in Korean patients with non-syndromic tooth agenesis." (PMID 39941240, 2025). "Most previous studies have investigated WNT10A mutations in patients with tooth agenesis using single nucleotide polymorphism (SNP) arrays or exome sequencing." (PMID 39941240, 2025). "Previous studies that identified WNT10A mutations associated with tooth agenesis only identified mutations in exonic regions, excluding introns, or performed whole-genome sequencing (WGS), which resulted in significant data size and cost limitations." (PMID 39941240, 2025). "Within the context of tooth morphogenesis, the key mediator of WNT signaling is WNT10A, which is implicated in inherited tooth agenesis." (PMID 39941240, 2025). "Of these, family 6 with tooth agenesis and family 11 with high myopia and congenital deafness, had additional variants in WNT10A and COL11A1, respectively, accounting for their extraocular features." (PMID 40301690, 2025). "Pathogenic variants in the WNT10A gene are the most frequent cause of nonsyndromic tooth agenesis in humans, including the Japanese population." (PMID 38263268, 2024). "In this study, we identified a novel nonsense WNT10A variant, NM_025216.3(WNT10A_v001):c.1090A > T, which produces a C-terminal truncated gene product, p.(Lys364*), in a sporadic form of congenital tooth agenesis." (PMID 36702846, 2023). "It has been demonstrated that more than half of individuals with hypodontia and oligodontia are carriers of the WNT10A risk variants, comprising the most frequently observed p.Phe228Ile (rs121908120) and p.Cys107Ter (rs121908119)." (PMID 36294409, 2022). "In this study, we investigated four candidate genes MSX1, PAX9, AXIN2, and WNT10A in an Iranian family with hereditary non-syndromic tooth agenesis to find the variants responsible for tooth agenesis." (PMID 36561383, 2022). "On the other hand, the WNT10A mutation (p.Gly213Ser) is well documented to cause tooth agenesis with incomplete penetrance." (PMID 34834569, 2021). "The oligodontia phenotype often proved to be a dose effect of combining two defective WNT10A alleles from heterozygous parents, sometimes with hypodontia." (PMID 34593752, 2021). "Population-based studies have revealed that 28%–62% of tooth agenesis patients have with WNT10A variants." (PMID 33329022, 2020). "In our study, Patient 3 (3.II.2) and Patient 5 (5.II.3), who harbor the homozygous WNT10A c.637G > A and c.511C > T variants, respectively, have tooth agenesis and their phenotypes are more severe than the heterozygous individuals with the same variant." (PMID 33329022, 2020). "Using WNT10A target sequencing, significantly elevated frequencies of WNT10A variants were observed in the tooth agenesis group compared with the control group." (PMID 33329022, 2020). "Mutations of several genes such as PAX9, MSX1, AXIN2, KDF1 and WNT10A have been reported which are associated with non-syndromic tooth agenesis." (PMID 33014315, 2020). "This is in line with recent evidence that WNT10A mutations are a common cause of non-syndromic tooth agenesis." (PMID 26964878, 2016). "Mutations in the WNT10A gene cause a broad spectrum of ectodermal dysplasias, ranging from mild signs of ectodermal dysplasia such as hypodontia to syndromes like OODD and Schöpf-Schulz-Passarge syndrome (SSPS)." (PMID 26964878, 2016). "We characterized six families with isolated (nonsyndromic) tooth agenesis associated with WNT10A defects." (PMID 25629078, 2015). "In Family 3, we identified 4 WNT10A mutations potentially leading to tooth agenesis in the family, p.Cys107*, p.Gly165Arg, p.Phe228Ile, and p.Asn363His." (PMID 25629078, 2015).
tooth agenesis (continued). "WNT10A is a signaling molecule involved in tooth development, and WNT10A defects are associated with tooth agenesis." (PMID 25629078, 2015). "We identified WNT10A defects in six families with nonsyndromic tooth agenesis, including the novel WNT10A mutation (g.6825C>T, c.310C>T, p.Arg104Cys)." (PMID 25629078, 2015). "With the analyzed exome data, we first searched for mutations in genes known to be associated with tooth agenesis and found two reported WNT10A mutations, g.6836C>A, c.321C>A, p.Cys107* and g.14757T>A, c.682T>A, p.Phe228Ile." (PMID 25629078, 2015). "The results further confirm that other genetic factors influence the phenotypic expression in severe tooth agenesis patients with heterozygous WNT10A mutations." (PMID 24312213, 2013). "Digenic mutations of both EDA and WNT10A were identified in 2 of 88 (2.27%) isolated oligodontia cases and 4 of 26 (15.38%) syndromic tooth agenesis cases." (PMID 24312213, 2013). "More recently, WNT10A has been isolated and shown to improve the diagnostic yield of DNA testing in isolated nonsyndromic hypodontia." (PMID 24191202, 2013). "The other four EDA mutations identified in HED patients and the two WNT10A mutations have been reported in tooth agenesis patients previously." (PMID 24312213, 2013). "Therefore, while the WNT10A variant caused hypodontia in the current patient, the same variant can also cause oligodontia." (PMID 38263268, 2024). "Wnt10a is associated with both syndromic and non-syndromic tooth agenesis." (PMID 37194731, 2023). "The hypodontia may be related to WNT10A polymorphism both in Chinese and western population but WNT10A could also clear senescent synovial resident stem cells and protect cartilage integrity in knee OA joints." (PMID 36997944, 2023). "Furthermore, patient P3 is a heterozygous carrier of the WNT10A variant c.682T > A (p.Phe228Ile) known to evoke tooth agenesis or even HED when present in homozygous or compound-heterozygous states." (PMID 35923710, 2022). "However, the pathogenic mechanism of WNT10A-associated tooth agenesis is still unclear and needs to be further studied." (PMID 36553094, 2022). "In 2011, WNT10A was identified as the pathogenic gene of nonsyndromic tooth agenesis (NSTA)." (PMID 36553094, 2022). "In our seven WNT10A families there were six subjects with oligodontia caused by biallelic defects, three caused by single allele defects, and two subjects with biallelic defects that showed a less severe hypodontia phenotype." (PMID 34593752, 2021). "The difference in WNT10A allele frequencies among different ethnic groups may also partly explain the diverse prevalence of tooth agenesis on different continents." (PMID 33329022, 2020). "Only thirty-eight variants are enlisted in WNT10A for isolated tooth agenesis phenotypes." (PMID 31652981, 2019). "In this study, digenic mutations of both WNT10A and EDA caused isolated and syndromic tooth agenesis, and the protein structure analyses indicated that all the WNT10A and EDA mutations may affect protein function." (PMID 24312213, 2013). "Recently, WNT10A mutations were identified in more than half of isolated hypodontia cases." (PMID 24312213, 2013). "Therefore, variants in WNT10A are a frequent cause of isolated hypodontia." (PMID 37361548, 2023). "Therefore, we hypothesized that EDA mutations interact with WNT10A mutations to play a role in tooth agenesis." (PMID 24312213, 2013). "WNT10A (chromosome 2q35, OMIM 606268) has been investigated in many studies, and more than 50% of the cases of tooth agenesis have been attributed to WNT10A mutations." (PMID 39941240, 2025). "Based on previous research, future studies should investigate the interactions between WNT10A and other genes involved in tooth agenesis." (PMID 39941240, 2025). "The yield of molecular testing of isolated hypodontia increased from 15 to 71% by including WNT10A in the DNA diagnostics." (PMID 37361548, 2023).
tooth agenesis (continued). "It is noteworthy that in our hypodontia patient with the CPB missense variant located within the HAT domain (p.Glu1560Lys), a recurrent pathogenic variant of WNT10A was also detected." (PMID 36294409, 2022). "Of these, EDA, EDAR, EDARADD, and WNT10A are candidate genes of both non‐syndromic tooth agenesis and syndromic tooth agenesis (STA)." (PMID 33943035, 2021). "Among several genes involved in tooth development, mutations in MSX1, PAX9, AXIN2, WNT10A, EDA and KDF1 have been reported to play a role in tooth agenesis 6–13." (PMID 33014315, 2020). "Research has identified an association between mutations in MSX1, PAX9, EDA, AXIN2, WNT10A, WNT10B and LRP6 and human tooth agenesis." (PMID 31914153, 2020). "Human genetic studies have identified familial tooth agenesis genes, such as Wnt10a, Pax9, and Msx147–52." (PMID 31492950, 2019). "In this study, we identified three EDA, one EDAR and two WNT10A mutations in two patients with X-linked hypohidrotic ectodermal dysplasia (XLHED) and four patients with non-syndromic tooth agenesis (NSTA)." (PMID 28981473, 2017). "The proband was screened for mutations of genes previously related to tooth agenesis (i.e., PAX9, AXIN2, EDA, WNT10A, etc.)by targeted exome sequencing (TES), with next generation technology." (PMID 27917906, 2016). "Mutations and genetic variants of this pathway, such as WNT10A, AXIN2 and LRP6, have all been well recognized as susceptibility factors of tooth agenesis." (PMID 27362534, 2016). "The importance of WNT10A for tooth agenesis is in line with its rather specific expression in the epithelial signaling centers important for tooth development." (PMID 23991204, 2013). "Digenic mutations of both WNT10A and EDA were identified in 2 of 88 (2.27%) isolated oligodontia cases and 4 of 26 (15.38%) syndromic tooth agenesis cases." (PMID 24312213, 2013). "In conclusion, this is the first study to report two simultaneous gene mutations of EDA and WNT10A in HED and isolated tooth agenesis patients." (PMID 24312213, 2013). "We found that six participants harbored digenic mutations in both WNT10A and EDA: two of them had isolated oligodontia and the others had syndromic tooth agenesis." (PMID 24312213, 2013). "In this study, we investigated the contribution of WNT10A, EDA, EDAR and EDARADD mutations in patients with isolated or syndromic tooth agenesis." (PMID 24312213, 2013). "Several of the mutations have been detected in multiple studies and thus the high contribution of WNT10A to tooth agenesis is most apparently based on the presence, and even with moderate frequencies, of the disease causing alleles in all studied populations." (PMID 23991204, 2013). "More recently, mutations in isolated tooth agenesis have been identified in EDA (ENSG00000158813, OMIM 313500) and WNT10A (ENSG00000135925, OMIM 606268)." (PMID 23991204, 2013). "Heterozygote genotypes of WNT10A – including p.G165R - were observed in 19 probands with severe tooth agenesis and two other probands, which increased involvement of this gene to 23% of all probands and to 35% of those with a severe phenotype." (PMID 23991204, 2013). "At present, mutations causing non-syndromic tooth agenesis have been identified in MSX1, PAX9, AXIN2, EDA, and WNT10A." (PMID 23227268, 2012). "In this study, we performed mutational profiling of WNT10A in the saliva of Korean children and adolescents with non-syndromic tooth agenesis." (PMID 39941240, 2025). "In this family, Sanger sequencing detected no mutations in PAX9, AXIN2, MSX1, or WNT10A, which were previously reported as gene candidates for isolated tooth agenesis." (PMID 34545288, 2021). "Particularly, heterozygous WNT10A mutations have been known to cause mild hypodontia and sometimes no missing teeth." (PMID 34834569, 2021).
tooth agenesis (continued). "The aim of the present study was to identify the mutations in the candidate genes, PAX9, MSX1 and WNT10A, responsible for tooth agenesis in 4 Iranian families with hereditary pattern of non-syndromic tooth agenesis." (PMID 33014315, 2020). "Mutations in WNT10A have been proposed to be the most common cause of nonsyndromic tooth agenesis (NSTA)." (PMID 33329022, 2020). "This study verifies the fact, collected by other authors around the world, that pathogenic variants in WNT10A, EDAR, and EDA are the most frequently known causes of autosomal recessive hypodontia/oligodontia, autosomal recessive HED, X-linked HED, and X-linked isolated tooth agenesis." (PMID 31652981, 2019). "Congenital tooth agenesis is caused by mutations in the MSX1, PAX9, WNT10A, or AXIN2 genes." (PMID 26030286, 2015). "Recently, WNT10A, belonging to the Wnt pathway, became a focal candidate gene for tooth agenesis." (PMID 26406231, 2015). "However, among those 119 sequence variants a c.956G>T mutation in X-linked EDA1 was the unique one among six candidate genes (viz.PAX9, MSX1, AXIN2, WNT10A, EDAR and EDA1) associated with non-syndromic tooth agenesis known so far." (PMID 25203534, 2014). "This is the first study to show that simultaneous WNT10A and EDA mutations could lead to tooth agenesis in the Chinese population." (PMID 24312213, 2013). "Thus, WNT10A has the most significant contribution of so far identified genes to tooth agenesis, in line with previous reports." (PMID 23991204, 2013). "WNT10A and EDA digenic mutations could result in oligodontia and syndromic tooth agenesis in the Chinese population." (PMID 24312213, 2013). "To date, mutations in AXIN2 (axis inhibition protein 2), EDA (ectodysplasin A), MSX1 (msh homeobox 1), PAX9 (paired box 9) and WNT10A (wingless-type MMTV integration site family, member 10a) have been demonstrated to be associated with non-syndromic tooth agenesis." (PMID 24278334, 2013). "However, it was later demonstrated that defects in WNT10A are frequently associated with tooth agenesis without or with only minor signs of ectodermal dysplasia, and that these account for a significant majority of FTA cases." (PMID 34834569, 2021). "All variants were analyzed based on bioinformatics websites and Iranian gene databases, and as a result, it was revealed that variants of PAX9, MSX1 and WNT10A may not play a role in non-syndromic tooth agenesis among Iranian cases." (PMID 33014315, 2020). "In conclusion, the variants found in the PAX9, MSX1 and WNT10A genes may not play a role in nonsyndromic tooth agenesis, but further studies should be performed to explore the exact association between these SNPs and the disease." (PMID 33014315, 2020). "Furthermore, WNT10A variations contributed to severity of tooth agenesis in Song’s study." (PMID 27362534, 2016). "The genetic basis of tooth agenesis is well-established, with several genes identified as controlling factors, namely MSX1, PAX9, AXIN2, EDA, IRF6, FGFR1, and WNT10A." (PMID 40040530, 2025). "Many genes have been reported as etiologic agents of tooth agenesis, including MSX1, PAX9, LRP6, WNT10A, and WNT10B13." (PMID 38263268, 2024). "Several genes, including MSX1, PAX9, AXIN2, WNT10A and EDA have been reported to involve in tooth agenesis." (PMID 33014315, 2020). "PAX9, MSX1, AXIN2, WNT10A and EDA have been experimentally established for congenitally missing teeth like hypodontia and oligodontia." (PMID 25203534, 2014). "WNT10A, EDA, EDAR and EDARADD were sequenced in 88 patients with isolated oligodontia and 26 patients with syndromic tooth agenesis." (PMID 24312213, 2013). "Mutations in PAX9, MSX1, WNT10A, and AXIN2 genes are most commonly associated with non-syndromic tooth agenesis in the literature." (PMID 36561383, 2022). "MSX1, PAX9, AXIN2, WNT10A, and EDA are proven candidate genes for familial tooth agenesis." (PMID 23227268, 2012).